TLR4 (toll like receptor 4)
Diseases named in the same sentence as TLR4 in open-access papers (continued):
Sharing a sentence is not in itself a finding about the gene and the disease.
Sepsis (continued). "One of the important DAMPs is HMGB1 - a DNA binding protein that can be released from damaged cells under stress and activate tubular epithelial cells by interacting with TLR4 in sepsis." (PMID 33362762, 2020). "The NF-κB pathway, a typical inflammatory signaling pathway, can be activated by TLR4 and lead to the excessive release of proinflammatory cytokines leading to secondary sepsis myocardial injury." (PMID 32908632, 2020). "TLR4 is a widely investigated TLRs in sepsis, which is a key molecule in the innate immune system and the development of sepsis." (PMID 32455124, 2020). "It was proven that antibody-mediated neutralization of systemic CD14 modulates the TLR4 signaling pathway induced by E. coli-derived LPS or virulent E. coli in a pig model of sepsis." (PMID 32842482, 2020). "During sepsis, platelet TLR4 activation induces platelet binding to adherent neutrophils, leading to robust neutrophil activation and NET formation in liver sinusoids and pulmonary capillaries, which facilitate bacterial capture." (PMID 32645848, 2020). "Current evidence suggests that the TLR4 signaling pathway is critically involved in the inflammatory response in the CLP sepsis model and the LPS-induced AKI model." (PMID 33287398, 2020). "TLR4 interference have been regarded as a potential therapeutic target for sepsis as well as sepsis-induced organ injury." (PMID 32099901, 2020). "In sepsis, lipopolysaccharide (LPS) binding to Toll-like receptor 4 (TLR4) induces NF-κB signaling, which induces auto-amplification of cytokine production (a process also termed ‘cytokine storm’;)." (PMID 33287422, 2020). "Regarding the importance of Nrf2 signaling for preventing inflammation, NADPH oxidase-dependent ROS mediate amplified toll-like receptor 4 signaling and sepsis-induced mortality in Nrf2(−/−) mice." (PMID 33158207, 2020). "LPS is a classic TLR4 agonist which can induce an immediate and robust inflammatory response thus stimulating activation of the innate immune system in human sepsis." (PMID 33194004, 2020). "The findings were consistent between the in vitro and in vivo models; both pre- and post-transcriptional levels of HMGB1, TLR4, and IL-33 were significantly downregulated in the sesamin-treated sepsis group." (PMID 32893702, 2020). "In sepsis, platelets can be stimulated by LPS via TLR4, resulting in primed platelet activation elicited by other agonists." (PMID 32013235, 2020). "Our group previously demonstrated that during an endotoxic condition, a model of study of sepsis in vitro, EC suffers a transition to fibroblast by the activation of toll-like receptor 4 (TLR4) and increased ROS production through NAD(P)H activation." (PMID 33291725, 2020). "Neutralization of TLR4 signaling holds promise for diseases, such as colitis, chronic pain, and sepsis." (PMID 32927756, 2020). "Sulfur dioxide attenuates sepsis-induced cardiac dysfunction by inhibiting inflammation via the TLR4/NLRP3 signaling pathway." (PMID 33324236, 2020). "For example, the administration of miR-146a was found to reduce proinflammatory cytokines (TNF-α, IL-1β, and IL-1α) and inflammatory edema in an LPS-induced model of sepsis in rats by targeting the TLR-4/NFκB pathway." (PMID 31671621, 2019). "Here, we demonstrated that THOP1-/- mice have slightly better survival and behavior performance seven days after polymicrobial sepsis induction, with slightly lower expression of TLR4 and TNF-α in dorsal hippocampus." (PMID 31431000, 2019). "In summary, this study provides evidence that TSLP is produced via TLR4 signaling in macrophages during sepsis." (PMID 31480519, 2019). "In term neonates with late-onset sepsis, TLR4 expression was increased in infants with positive blood cultures and TLR2 expression was raised in those with clinical sepsis." (PMID 31611734, 2019).
Sepsis (continued). "On the other hand, the emerging role of TLR4 and NLRP3 activation in inflammatory and autoimmune diseases, such as sepsis and lupus, among others has suggested the use of TLR4 and NLRP3 antagonists in therapy." (PMID 31062071, 2019). "Previous studies have shown that baseline monocyte expression of TLR2 and TLR4 in patients with sepsis in intensive care is significantly up-regulated compared with healthy controls." (PMID 31612119, 2019). "During sepsis, administration of α-toxin promotes lethality and tissue injury accompanied by accelerated production of inflammatory cytokines in a TLR4-dependent manner." (PMID 30729183, 2019). "Because of their impact on immune response, synthetic lipid A modifications have been assessed as a potential therapy for sepsis, specifically as TLR4 blockades to prevent inflammatory downstream effects." (PMID 31491842, 2019). "The binding of LPS to TLR4 enhances the translocation of NF-κB to nuclei, and this produces a pro-inflammatory cytokine shower in sepsis." (PMID 31671563, 2019). "Previous experiments have confirmed that extracellular HMGB1 is a lethal inflammatory mediator in late sepsis as it activates the inflammation-related signalling pathways by binding with its specific receptors RAGEs/TLR-2/TLR-4." (PMID 31781288, 2019). "Previous research indicates that cardiac inflammation during sepsis and trauma condition such as burn injury is mediated at least by the activation of toll-like receptor 4 (TLR4)/CD14 complex and the increase in mitochondrial DAMPs." (PMID 30744190, 2019). "In polymicrobial sepsis, the activation of TLR4 in macrophages is important for an effective bacterial phagocytosis." (PMID 31348811, 2019). "According to Haak and Wiersinga (2017), probiotics further influence the prognosis in sepsis by down-regulating colonic TLR-2/TLR-4 via MyD88 and by mitigating the systemic pro-inflammatory response." (PMID 31447793, 2019). "By employing TLR4−/− mice as the model, more evidence has shown that blocking TLR4 protects mice from severe kidney damage in LPS-induced sepsis." (PMID 30915370, 2019). "Many previous studies have demonstrated the role of TLR2 and TLR4 inhibition in the pathogenesis of sepsis." (PMID 30814582, 2019). "Cpb1 binds to and activates C3aR and thus regulates innate immune signaling, and caspase-11 expression amplifies MAPK activity and IFN-α-receptor activation downstream of TLR4 and influences disease severity in LPS-induced sepsis and endotoxemic mice." (PMID 31671729, 2019). "Animal models revealed that thrombocytopenia in sepsis is largely TLR4-dependent, which suggests that immune-mediated platelet activation represents a main cause for the drop in platelet count." (PMID 31379873, 2019). "The results of the present study provided the first evidence of SND that protects against sepsis and sepsis-induced adrenal dysfunction in rat model by downregulation of TLR4." (PMID 30018657, 2018). "In mammals, knockout of the LPS receptor TLR4 confers resistance to bacteria induced sepsis, suggesting that dramatic LPS-induced pro-inflammatory responses are detrimental in sepsis." (PMID 30542348, 2018). "Lipopolysaccharide (LPS), the major component of the outer membrane of Gram-negative bacteria, is a critical factor in the pathogenesis of sepsis, which is sensed by Toll-like receptor 4 (TLR4)." (PMID 30567900, 2018). "Patients whose TLR4 concentrations changes evolved towards one attractor survived sepsis (patients #1, 4, 5, and 8)." (PMID 29996939, 2018). "Circulating histones contribute to inflammation, and to lethality in sepsis, a hyperinflammatory condition, by interacting with specific receptors, notably toll-like receptor 4 (TLR4)." (PMID 29997623, 2018). "Although no clinical studies of TLR4 modulation in intestinal inflammation have yet been performed, the TLR4 antagonist eritoran tetrasodium (E5564) has been used in a phase 3, randomized, double-blind, placebo-controlled clinical trial of sepsis." (PMID 29515999, 2018).
Sepsis (continued). "In sepsis, toll-like receptor 4 (TLR4) is a key sensor for signaling the presence of Gram-negative bacteria." (PMID 29996939, 2018). "Cells from TLR4-null mutant mice and cells from signaling inactive mice fail to form LD after stimulation by LPS or during experimental sepsis, establishing the dependency of TLR4 for macrophages LD formation." (PMID 29875768, 2018). "In general these studies have shown that TLR2 and TLR4 contribute to high mortality and multiorgan dysfunction in animal models of polymicrobial sepsis." (PMID 30364002, 2018). "This study aimed to evaluate the effects of TLR4 increased expression and intracellular trafficking on the course and outcome of sepsis." (PMID 29996939, 2018). "In sepsis, Tim-3 signaling in macrophages also inhibited LPS/TLR4-mediated pro-inflammatory cytokine production." (PMID 30687334, 2018). "TLR4 also correlates with the corticosterone secretion and the impaired adrenal glucocorticoid responses in sepsis." (PMID 30018657, 2018). "Of the TLR, TLR4 is demonstrated as not only one of the most substantial receptors in activation of the HPAA during sepsis, but also a critical receptor to regulate the immune-adrenal crosstalk in sepsis." (PMID 30018657, 2018). "Efforts have been dedicated to testing anti-TLR4 agents, such as eritoran, a myeloid differentiation protein (MD) 2-TLR4 antagonist, in patients with severe sepsis." (PMID 29977913, 2018). "Unfortunately, results were disappointing, suggesting that sepsis is a very complex disease in which the early occurring “cytokine storm” is dependent only in part on TLR4 and is rapidly followed by profound immunosuppression that affects patients' survival." (PMID 29686833, 2018). "Similar researches have showed that rhein can prevent LPS-induced acute kidney injury by inhibiting NF-κB activities and inhibit LPS-induced intestinal injury during sepsis by blocking TLR4- NF-κB pathway." (PMID 29385192, 2018). "Throughout the continuum of sepsis, complete TLR4 signaling includes not only the initial surface-bound pro-inflammatory signaling, but also its subsequent endocytosis and intracellular trafficking." (PMID 29996939, 2018). "Our findings show that fEVs cause sepsis-like systemic inflammation, when introduced intraperitoneally, a process regulated by TLR2 and TLR4." (PMID 30131776, 2018). "Along these lines, TLR4 knock-out animals exhibit lesser sepsis-induced muscle inflammation and are also less susceptible to ventilator-induced diaphragm dysfunction." (PMID 30067847, 2018). "Confirming this model with in vivo measurements of TLR4 intracellular trafficking rates would provide further insight into their contribution to sepsis onset and progression." (PMID 29996939, 2018). "TLR4 plays a key role in the sepsis model, although its role in the regulation of inflammation varies with the cell type." (PMID 29977913, 2018). "Collectively, these data show: that prolonged MTV ventilation exacerbates ALI caused by extrapulmonary sepsis; and an important positive feedback role for the WISP1–integrin β5 pathway in TLR4-mediated exacerbations to this two-hit model." (PMID 30445996, 2018). "Studies in larger cohorts have previously demonstrated increased platelet TLR-4 expression in patients suffering from sepsis." (PMID 29734352, 2018). "For example, TLR4 inhibition plays different roles in the mild or severe cecal ligation perforation (CLP) model of sepsis." (PMID 29977913, 2018). "In sepsis, TLR4 independent and myeloid differentiation primary response protein 88 (MyD88) dependent activation controls MDSC functions." (PMID 30405617, 2018). "Suppression of TLR-4 activation, pro-inflammatory cytokine release, and developing endotoxin tolerance is important in limiting the adverse effects of sepsis." (PMID 30390640, 2018). "Gram-negative bacterial lipopolysaccharide (LPS) is both a central mediator of sepsis and a canonical inducer of acute inflammation via Toll-like receptor 4 (TLR4)." (PMID 30399158, 2018).
Sepsis (continued). "TLR-4/NF-κB pathway is one of the most important signaling pathways in the inflammatory response of sepsis." (PMID 29440462, 2018). "In particular, TLR4 experiences a significant upregulation in mRNA production and presentation to the cell surface at the initial stages of sepsis in both humans and experimental models." (PMID 29996939, 2018). "Our finding that blockade of the TLR4–NF-κB pathway or TNF-α can reverse impaired myogenesis suggests a new set of drug targets for clinical intervention in sepsis- or metabolic endotoxemia-induced muscle debilitation." (PMID 28742154, 2017). "A murine sepsis model in C57BL/6 mice injected with LPS stimulated TLR4 and activated SIRT1, which induced NF-κB p65 deacetylation and deactivation thus inhibiting pro-inflammatory gene expression." (PMID 28579962, 2017). "HMGB1 further plays an important role in sepsis by facilitating the transfer of LPS to CD14 to initiate a TLR4-dependent proinflammatory response." (PMID 29261777, 2017). "Here we will review the experimental evidence supporting a role for TLR4 in sepsis‐induced AKI (SI‐AKI) with emphasis on described mechanisms of action." (PMID 27602552, 2017). "Histones have also been proposed to be ligands for TLR4 and are found in the blood during sepsis following release from neutrophils or necrotic cells." (PMID 29170605, 2017). "One example of a structural analog is eritoran, a TLR4 antagonist that inhibits LPS-induced inflammation and improves survival in a mouse model of sepsis." (PMID 28348558, 2017). "Vogl and colleagues showed that S100A8/A9 amplifies phagocyte activation during lipopolysaccharide-induced sepsis via activation of TLR-4 upstream of TNF-α response." (PMID 28672877, 2017). "Eritoran, an antagonist of TLR4, exhibits positive results in phase I and phase II clinical trials of severe sepsis, but it has failed in a phase III-randomized controlled trial." (PMID 29075648, 2017). "Endocytosis of TLR4 is not only crucial to prevent severe chronic inflammatory conditions such as sepsis, but also to guarantee a sustained immune response to suppress an ongoing infection." (PMID 27628304, 2017). "Circulating extracellular histones in plasma have been detected in septic patients, and it interacts with TLR2 and TLR4 on a variety of different cell types and contributes to endothelial dysfunction, organ failure, and death in experimental sepsis." (PMID 28970829, 2017). "Based on this particular mode of action, we considered that Fh12 is an attractive molecule with potential to develop a drug against sepsis, UC or any other inflammatory disease in which TLR4 is involved." (PMID 28710478, 2017). "Coagulation abnormalities are commonly observed in severe sepsis, and the presence of TLR4 on platelets can be considered a link between disseminated intravascular coagulation and sepsis." (PMID 28976997, 2017). "Although dispensable for the process of DC maturation, TLR2 and TLR4 play key roles in the mechanisms resulting in the depletion of spleen DC following polymicrobial sepsis." (PMID 29075648, 2017). "Therapeutic effects of treatment with anti-TLR2 and anti-TLR4 monoclonal antibodies have been investigated in a mouse study against polymicrobial sepsis." (PMID 29096690, 2017). "Given the importance of C5a-C5aR1 interactions in promoting the onset and development of sepsis, we sought to investigate the regulation of IL-1β production by C5aR1 signaling in a TLR4-mediated, mouse endotoxemia model." (PMID 27382187, 2016). "Stimulation of TLR4+ can induce potent responses such as sepsis and inflammation induced damage by release of pro inflammatory cytokines." (PMID 27606818, 2016). "In in vitro and in vivo models of sepsis, LPS has been shown to activate platelets and PMNs via toll-like receptor 4 (TLR4) to induce NETosis." (PMID 27446071, 2016). "TLR4 is activated by bacterial lipopolysaccharide (LPS) and is, therefore, suggested to be most relevant in sepsis." (PMID 26761003, 2016).
Sepsis (continued). "The endotoxin is one of the major triggers of inflammatory responses in sepsis, as it is known to product and releases a large number of inflammatory cytokines that activate potent immune response through the activation of Toll-like receptor 4 (TLR4)." (PMID 27027358, 2016). "Malnutrition, high plasma endotoxin and sCD14 levels, single TLR4+896A/G or CD14-159C/T variant allele carriers and double variant allele carriers are significant predictive factors for the development of severe sepsis among them." (PMID 27861595, 2016). "Of note, the blockade of platelet TLR4 markedly impairs NETosis and this has been suggested as a new therapeutic approach for sepsis." (PMID 27458459, 2016). "For example, the role of the endogenous TLR4 and RAGE agonist HMGB1, a molecule previously associated with sepsis, now has emerged as an important participant in mediating inflammatory and neuroinflammatory pain states." (PMID 27781082, 2016). "Both on the CD16- and CD16+ monocyte, the significantly lower baseline and LPS-stimulated HLA-DR expression were observed in cases carrying variant TLR4+896A/G or CD14-159C/T allele carriers and severe sepsis." (PMID 27861595, 2016). "We sought to detect the effect of global genetic ablation of TLR4 or CD14 (TLR4−/−, CD14−/−) in a clinically relevant model of polymicrobial sepsis caused by CLP in mice." (PMID 27349568, 2016). "Considerable research has focused on the molecular mechanism of LPS-induced sepsis, especially the cellular signaling of activation of toll-like receptor 4 (TLR4) in the past few years." (PMID 27563672, 2016). "Some TLR4 modulators are undergoing preclinical and clinical evaluation for the treatment of sepsis, inflammatory diseases, cancer and rheumatoid arthritis." (PMID 27483231, 2016). "By contrast, with the growing incidence of sepsis, in which free LPS can bind to and activate Toll-like receptor 4 on many cell types, the roles of LPS on endogenous BMSCs and other cell types are worth detailed investigation." (PMID 27557078, 2016). "It was demonstrated that CCR2 is induced on the neutrophil surface in mice and patients with sepsis in a TLR2- or TLR4-dependent manner." (PMID 27199981, 2016). "Significantly, increased proportion of CD16+ monocyte subsets were observed in TLR4+896A/G or CD14-159C/T variant allele carriers and severe sepsis cases." (PMID 27861595, 2016). "The finding that activation of TLR4 on platelets activates the release of NETs was a significant shift in understanding the inflammatory response to sepsis." (PMID 27458459, 2016). "Accumulating data showed that inhibition of TLR4 signaling by means of antibodies or soluble decoy receptors have proven to obtain a clinical benefit to sepsis." (PMID 28082984, 2016). "This molecule, called Toll-like receptor 4 (TLR4) is a key mediator of the effects of sepsis in patients critically sick with infections." (PMID 27784777, 2016). "The phagocytic abilities of CD16- monocyte were significantly decreased among cases carrying variant TLR4+896A/G or CD14-159C/T allele and severe sepsis." (PMID 27861595, 2016). "Nonetheless, above mention phenomena was disappeared among CD16- monocytes collected from cases carrying variant TLR4+896A/G or CD14-159C/T allele and severe sepsis." (PMID 27861595, 2016). "In the current study, we pursued further aspects of WISP1 modulation of TLR signaling in lungs of mice after sepsis and TLR4 mediated release of TNF-α in macrophages." (PMID 27349568, 2016). "Another study revealed miR-146a to be a dual transcriptional regulator of TLR4 in the human monocytic cell line THP-1 sepsis cell model." (PMID 26761003, 2016). "THBD is a multifunctional immunomodulator and a putative sepsis marker which has recently been suggested to be a component of the LPS-receptor complex CD14/TLR4/MD-2." (PMID 25706641, 2015). "Since TLR4/MyD88/MAPK/NF-κB signal pathway plays a critical role in regulating the generation of inflammatory cytokines in endotoxemia or sepsis." (PMID 25929655, 2015).